TRIM44 (tripartite motif containing 44)
Diseases named in the same sentence as TRIM44 in open-access papers (continued):
Sharing a sentence is not in itself a finding about the gene and the disease.
glioma (7 papers, 2020 to 2024). A benign or malignant brain and spinal cord tumor that arises from glial cells (astrocytes, oligodendrocytes, ependymal cells). "TRIM44 expression was found increased in GBM and GSC cell lines compared to normal human astrocytes and TRIM44 knockdown resulted in glioma cell proliferation and migration inhibition, downregulation of EMT marker genes and activation of apoptotic pathways." (PMID 36139694, 2022). "By detecting TRIM44 protein expression in glioma tissues and cells, we discovered that TRIM44 was obviously overexpressed compared with corresponding controls." (PMID 34150336, 2021). "Collectively, our results indicated that circ_0030018 promoted glioma proliferation and metastasis by regulating the miR-194-5p/TRIM44 axis." (PMID 34150336, 2021). "Knock-down of TRIM44 in glioma cells induces an increase in p21/p27 expression,and then it inhibited cell division." (PMID 32503466, 2020). "Further, the critical p21/p27 regulator AKT is inactivated after TRIM44 is knocked down, but it is activated in glioma cells that overexpress TRIM44." (PMID 32503466, 2020). "It has been reported that circ0030018 is upregulated in glioma and silencing circ0030018 could hinder glioma progression via regulating the miR‐194‐5p/TRIM44 pathway, indicating the potential role circ0030018 played in glioma." (PMID 37250146, 2023). "Overexpressed TRIM44 reversed the inhibition effect of miR-194-5p on glioma cell progression." (PMID 34150336, 2021). "Animal experiments suggested that circ_0030018 knockdown could reduce glioma tumor growth through regulating miR-194-5p and TRIM44." (PMID 34150336, 2021). "In addition, other studies confirmed that the high TRIM44 expression was closely related to the proliferation and cell cycle progression of glioma." (PMID 34150336, 2021). "Our 8data showed that circ_0030018 enhanced glioma progression by sponging miR-194-5p to regulate TRIM44, indicating that circ_0030018 might be a potential treatment target for glioma." (PMID 34150336, 2021). "Consistent with the previous conclusions, our study suggested that TRIM44 deletion could inhibit glioma progression." (PMID 34150336, 2021). "The rescue experiments revealed that TRIM44 could reverse the inhibition effect of miR-194-5p on glioma progression, which illuminated that miR-194-5p targeted TRIM44 to participate in the regulation of glioma." (PMID 34150336, 2021). "In addition, TRIM44 was a target of miR-194-5p, and its downregulation could repress glioma cell progression." (PMID 34150336, 2021). "TRIM24, TRIM47, TRIM44, TRIM31, TRIM14, TRIM21, and TRIM28 have exhibited significant prognostic value regarding OS and/or PFS of glioma patients." (PMID 36139694, 2022).
melanoma (7 papers, 2019 to 2022). A malignant, usually aggressive tumor composed of atypical, neoplastic melanocytes. "Amplified TRIM44 expression was also discovered in melanoma tissues, and overexpression of TRIM44 is associated with a malignant phenotype of melanoma." (PMID 32503466, 2020). "The present study demonstrates that TRIM44 is significantly amplified in melanoma tissues, and overexpression of TRIM44 is associated with a malignant phenotype of melanoma." (PMID 30922374, 2019). "Recently, miR-26b-5p has been shown to target the MAPK and AKT/mTOR signaling pathways by binding to the 3′ UTR of TRAF5 or TRIM44, respectively, which are involved in the malignant progression of melanoma cells." (PMID 32825219, 2020). "Here, qRT-PCR and Western blot results indicated that TRIM44 expression was significantly upregulated in melanoma tissues relative to matched peritumorous tissues." (PMID 30922374, 2019). "Our present study is the first to show that TRIM44 is significantly upregulated in melanoma tissues using a large number of clinical samples, a result that is consistent with that of the public database." (PMID 30922374, 2019). "In this study, we explored the expression and biological functions of TRIM44 using a comprehensive investigative approach that included clinical melanoma samples along with cellular and animal models." (PMID 30922374, 2019). "TRIM44, regulated by miR-26b-5p, promotes melanoma progression by stabilizing TLR4, which then activates the AKT/mTOR pathway." (PMID 30922374, 2019). "By retrieving the database, we found that TRIM44 is significantly upregulated in multiple cancers, including melanoma." (PMID 30922374, 2019). "We found that miR-26b-5p was downregulated in the melanoma tissue samples compared with paired paratumoral tissue samples, and that there was a negatively relationship between the expression of TRIM44 mRNA and miR-26b-5p (p = − 0.047." (PMID 30922374, 2019). "Histochemical analyses found that TRIM44 was primarily expressed in the cytoplasm and there was significantly higher TRIM44 expression in melanoma samples compared with matched normal tissues." (PMID 30922374, 2019). "Clinically, we find that high levels of TRIM44 combined with upregulation of TLR4 serves as a promising prognostic indicator in melanoma patients." (PMID 30922374, 2019). "TRIM44 shows promise as a prognostic predictor and a therapeutic target for melanoma patients." (PMID 30922374, 2019). "We found that TRIM44 was commonly amplified in melanoma tissues compared with paratumoral tissues." (PMID 30922374, 2019). "Importantly, high level of TRIM44 induced melanoma cell epithelial-mesenchymal transition (EMT), which is one of the most important mechanisms for the promotion of tumor metastasis." (PMID 30922374, 2019). "Importantly, high levels of TRIM44 induced melanoma cell EMT, which is one of the most important mechanisms for the promotion of tumor metastasis." (PMID 30922374, 2019). "First, TRIM44 expression was detected in five melanoma cell lines." (PMID 30922374, 2019). "Moreover, we found that elevated TRIM44 promoted cell proliferation, invasion, migration and apoptosis resistance in vitro, and promoted melanoma growth and metastasis in vivo." (PMID 30922374, 2019). "Importantly, we found that TRIM44 was an independent indicator of prognosis for melanoma patients." (PMID 30922374, 2019). "Moreover, we demonstrated that TRIM44 is the target of miR-26b-5p, which is significantly downregulated in melanoma tissues and may be responsible for the overexpression of TRIM44." (PMID 30922374, 2019). "Importantly, TRIM44 may be a useful prognostic indicator for melanoma and provides a potential new target for melanoma therapy." (PMID 30922374, 2019). "Taken together, these data indicate that upregulation of TRIM44 activates the AKT/mTOR pathway, which in turn promotes melanoma cell EMT." (PMID 30922374, 2019).
melanoma (continued). "To further explore the relationship between TRIM44 and TLR4, we quantified TRIM44 and TLR4 expression in 20 melanoma tissue samples." (PMID 30922374, 2019). "This suggests that overexpression of TRIM44 and TLR4 are indicators of a poor prognosis in melanoma patients." (PMID 30922374, 2019). "Taken together, these results indicate that TRIM44 induces EMT, and thereby contributes to melanoma progression." (PMID 30922374, 2019). "TLR4 plays an important role in melanoma as well, because it interacts with TRIM44, a negative prognostic factor in melanoma." (PMID 33980826, 2021). "Importantly, univariate and multivariate analyses indicated that the TRIM44 level, Breslow depth, and TNM stage were independent indicators for melanoma patient prognoses." (PMID 30922374, 2019). "This cell morphology indicated that cells with high levels of TRIM44 develop an EMT-like phenotype, finding that was supported by immunofluorescence (lower) and immunohistochemistry analyses of subcutaneous xenograft melanoma tissues." (PMID 30922374, 2019). "Furthermore, we elucidated the mechanisms behind TRIM44-induced melanoma cellular EMT, as well as upstream TRIM44 regulators." (PMID 30922374, 2019). "Of course, this post-translational modification may not limit to melanoma, as the TRIM44-AKT-mTOR axis is common in multiple tumors." (PMID 30922374, 2019).
multiple myeloma (6 papers, 2019 to 2025). "Here, we report that TRIM44 overexpression is associated with poor prognosis in a Multiple Myeloma Research Foundation (MMRF) cohort of 858 patients, persisting across primary and recurrent MM cases." (PMID 39273003, 2024). "In multiple myeloma (MM), TRIM44 is overexpressed in the osteoblastic niche of the bone marrow, allowing MM cells to compete with hematopoietic stem cells for niche support." (PMID 39273003, 2024). "We initiated our investigation into the prognostic significance of TRIM44 expression levels in MM patients by analyzing data from the Multiple Myeloma Research Foundation (MMRF) cohort, which comprised 858 patients." (PMID 39273003, 2024). "The upregulation of TRIM44 was determined to maintain myeloma cells to a quiescent state and reduce cell proliferation." (PMID 36072809, 2022). "Further investigations using bone biopsies of myeloma patients indicated that quiescent PKH+ myeloma cells expressed a higher number of a gene named TRIM44 compared to proliferating myeloma cells." (PMID 36072809, 2022). "In myeloma, hypoxia induces stem cell-like features and stabilisation of hypoxia inducible factor (HIF)1α by the deubiquitinase tripartite motif-containing protein 44 (TRIM44) maintains quiescence in vivo." (PMID 41091336, 2025). "TRIM44, a tripartite motif (TRIM) family member, is pivotal in linking the ubiquitin-proteasome system (UPS) to autophagy in multiple myeloma (MM)." (PMID 39273003, 2024).
viral infection (6 papers, 2016 to 2024). "Even though there is convincing evidence in TRIM44 function related to immune regulation and viral infection, only a handful of publications (total 8) are linked their functions to cancers." (PMID 30089913, 2019). "SRS2 group eQTL specificity was also seen for TRIM44, which promotes an enhanced cellular response to viral infection, and DDX24, which encodes a type I interferon-inducible DEAD-box protein RNA-helicase modulating IRF7 activity." (PMID 26917434, 2016). "Tripartite Motif-Containing 44 (TRIM44) is responsible for cancers, neurodegenerative diseases, and viral infections." (PMID 39772186, 2024). "Many studies reported that TRIM44 is involved in multiple disorders such as neurodegenerative diseases, cancers, and viral infections." (PMID 39772186, 2024). "Studies have reported that TRIM44 not only participates in the innate immunity against viral infection but also acts as a bridge between cellular autophagy and the ubiquitin–proteasome degradation system." (PMID 38731834, 2024). "Since it was first identified in the mouse brain, only a few studies have analyzed the functions of TRIM44, and these have mostly been in cancers or virus infection (17 total publications as of 2017)." (PMID 30089913, 2019). "Previous studies have demonstrated that TRIM44 was responsible for multiple disorders such as neurodegenerative diseases and viral infections." (PMID 29446253, 2018). "However, the role of Siniperca chuatsi TRIM44 (scTRIM44) during viral infection remains unclear." (PMID 39772186, 2024).
colorectal cancer (5 papers, 2018 to 2024). A primary or metastatic malignant neoplasm that affects the colon or rectum. "The inhibition of circRAD23B has been demonstrated to impede the advancement of colorectal cancer through the regulation of the miR-1205/TRIM44 axis." (PMID 38289973, 2024). "ELFN1-AS1 accelerated the proliferation and migration of colorectal cancer via regulation of miR-4644/TRIM44 axis." (PMID 37161577, 2023). "ELFN1-AS1 could promote proliferation, metastasis and exert anti-apoptosis effect by up-regulating TRIM44 by sponging miR-4644 in colorectal cancer." (PMID 35494024, 2022).
ovarian carcinoma (5 papers, 2019 to 2025). A malignant neoplasm originating from the surface ovarian epithelium. "Currently, there are many new diagnostic markers for ovarian cancer, such as mesothelin, TRIM44 and BCRA1 methylation." (PMID 31767040, 2019). "In fact, TRIM44 is associated with tumor progression in over 10 types of cancer, including thyroid cancer, esophageal cancer, gastric cancer, lung cancer, hepatocellular carcinoma, colorectal cancer, ovarian cancer, cervical cancer, breast cancer, prostate cancer, and testicular cancer." (PMID 40723250, 2025). "Previous research indicated elevated TRIM44 levels in ovarian cancer drive tumor progression via activating the NF-kB pathway." (PMID 41357604, 2025). "For example, TRIM44 has modulatory effects on tumor progression and is a potential indicator of unfavorable prognosis in epithelial ovarian cancer." (PMID 37514090, 2023). "The JAK/STAT pathway is regulated by ovarian cancer-derived exosomal circNFIX in human umbilical vein endothelial cells through the miR518a-3p/TRIM44 axis." (PMID 37514090, 2023). "TRIM44 expression is positively regulated via ovarian cancer-derived exosomal circRNA nuclear factor I X (circNFIX)." (PMID 37514090, 2023). "The downregulation of FRK by TRIM44 can also be observed in ovarian cancer." (PMID 40723250, 2025). "The miR-34a-5p may directly target TRIM44, thus inhibiting its activity and leading to suppression of ovarian cancer angiogenesis and malignant behavior." (PMID 37514090, 2023).
prostate carcinoma (5 papers, 2017 to 2025). A carcinoma that arises from epithelial cells of the prostate gland. "It has been reported that knockdown of TRIM44 inhibits the proliferation and invasion in prostate cancer cells." (PMID 30792262, 2019). "Intriguingly, YTHDF1 is also an upper stream regulator of TRIM44 in prostate cancer." (PMID 40723250, 2025). "Notably, it was also reported that knockdown of TRIM44 suppressed PI3K/Akt signaling in a prostate cancer cell line." (PMID 28885545, 2017).
glioblastoma (4 papers, 2021 to 2022). The most malignant astrocytic tumor (WHO grade IV). "MiR-101-3p promotes apoptosis of oral cancer cells by targeting BICC1, induces dysfunction of vascular endothelial cell by targeting tet methylcytosine dioxygenase 2, suppresses proliferation and metastasis of glioblastoma cells via targeting TRIM44." (PMID 34977016, 2021). "Likewise, miR-101-3p prevents EMT by targeting TRIM44 to reduce glioblastoma metastasis." (PMID 34307682, 2021). "Additionally, it was recognized that miR-101 could suppress the expression of tripartite motif containing 44 (TRIM44) by directly targeting its 3′-UTR, thereby reducing proliferation, migration, and invasion of glioblastoma cells." (PMID 36497343, 2022).
lymph node metastasis (4 papers, 2016 to 2024). "We also demonstrate for the first time that increased expression of TRIM44 is associated with poor differentiation, advanced pTNM stage, adenocarcinoma subtype, lymph node metastasis and, most importantly, poor survival." (PMID 27058415, 2016). "The present study shows that upregulation of TRIM44 is associated with poor differentiation, advanced pTNM stage, adenocarcinoma subtype, lymph node metastasis and, most importantly, unfavorable survival in patients with non-small cell lung cancer (NSCLC)." (PMID 27058415, 2016). "The results of the present study suggest that TRIM44 expression is predictive of NSCLC lymph node metastasis and poor survival." (PMID 27058415, 2016). "Additionally, increased levels of TRIM44 protein expression were correlated with lymph node metastasis, distant metastasis, increased tumor infiltration depth, advanced clinical stage, and recurrence." (PMID 39667820, 2024). "University Cox analysis also suggested that histological type, tumor size, and lymph node metastasis were correlated with patients’ OS and DFS except for TRIM44 expression." (PMID 30792262, 2019). "The TRIM44 expression level was statistically higher in patients with lymph node metastasis than in those without lymph node metastasis." (PMID 30792262, 2019). "Consistent with this, the results revealed that the mean relative expression of TRIM44 mRNA in tumor tissues from patients with lymph node metastasis was higher than that in tumor tissues from patients without lymph node metastasis (P = 0.034)." (PMID 27058415, 2016). "The results showed that TRIM44 protein expression was higher in NSCLC tissues from patients with lymph node metastasis (n = 10) than in those from patients without lymph node metastasis (n = 10) (P = 0.027)." (PMID 27058415, 2016). "Statistical analysis showed that TRIM44 expression was significantly correlated with FIGO stage (P<0.001), histological grade (P<0.001), and lymph node metastasis (P=0.032), but not with age, histological type, and tumor size." (PMID 30792262, 2019). "Statistical analysis showed that TRIM44 expression was significantly correlated with the International Federation of Gynecology and Obstetrics (FIGO) stage, histological grade and lymph node metastasis, but not with age, histological type, and tumor size." (PMID 30792262, 2019).
non-small cell lung carcinoma (4 papers, 2016 to 2025). A group of at least three distinct histological types of lung cancer, including non-small cell squamous cell carcinoma, adenocarcinoma, and large cell carcinoma. "In non-small cell lung cancer, upregulated TRIM44 promotes the migration and invasion of cancer cells via NF-kB signaling." (PMID 30089913, 2019).
intrahepatic cholangiocarcinoma (3 papers, 2019 to 2021). A carcinoma that arises from the intrahepatic bile duct epithelium in any site of the intrahepatic biliary tree. "A previous study confirmed that the MAPK signaling pathway was activated in intrahepatic cholangiocarcinoma cells by TRIM44, a protein involved in several kinds of cancers, to inhibit cell apoptosis and promote tumour invasion and metastasis." (PMID 33478536, 2021). "In intrahepatic cholangiocarcinoma, elevated TRIM44 worsened the progression by inducing cell EMT via MAPK signaling." (PMID 33391405, 2021).
lung adenocarcinoma (3 papers, 2022 to 2025). A carcinoma that arises from the lung and is characterized by the presence of malignant glandular epithelial cells. "TRIM44 was verified to be participated in the resistance of cisplatin in lung adenocarcinoma via deubiquitinating the K48-linked polyubiquitin chain with the ZnF UBP domain." (PMID 38978046, 2024). "Tripartite motif-containing 44 (TRIM44) has recently been implicated in various pathological processes in numerous cancers, including lung adenocarcinoma (LUAD); however, its functional roles in chemoresistance are poorly understood." (PMID 35541909, 2022).
renal cell carcinoma (3 papers, 2021 to 2025). "Knocking down TRIM44 inhibits the proliferation of renal cell carcinoma." (PMID 34677810, 2021).
testicular germ cell tumor (3 papers, 2019 to 2024). A germ cell tumor arising from the testis. "Additionally, elevated levels of TRIM44 are associated with poor prognosis in testicular germ cell tumors, esophageal squamous cell carcinoma, and gastric and breast cancers." (PMID 39273003, 2024). "In agreement with previous results, TRIM44 promotes cell proliferation and migration, and inhibits apoptosis in testicular germ cell tumor." (PMID 30792262, 2019).
laryngeal squamous cell carcinoma (2 papers, 2022 to 2023). A squamous cell carcinoma that arises from the larynx. "Tripartite motif-containing 44 (TRIM44) was found to be upregulated in 4 human laryngeal squamous cell carcinoma (LSCC) cell lines (AMC-HN-8, HEP-2, TU-212, and TU-686), and the knockdown of TRIM44 led to suppressed cell growth." (PMID 35158798, 2022). "Similarly, Li and colleagues verified that nuciferine has a significant effect on reducing the levels of Tripartite motif-containing 44 (TRIM44), leading to the inhibition of cell growth in laryngeal squamous cell carcinoma by suppressing the expression of phosphorylated p65." (PMID 37833979, 2023).